OPN1MW2 (opsin 1, medium wave sensitive 2)
Description:
G protein-coupled photoreceptor that selectively activates G(i) proteins in response to medium-wavelength (green) light, thereby decreasing intracellular cAMP levels. Activation occurs when the opsin-bound cis-retinal chromophore absorbs a photon and isomerizes to all-trans-retinal, inducing a conformational change in the opsin that triggers a G protein-mediated phototransduction cascade. Mediates visual perception of green light in cone photoreceptor cells.
Synonyms: GOP
Tractability: Small molecule: it belongs to a druggable protein family. Antibody: its Gene Ontology location is reachable by antibodies, with high confidence; UniProt places it where antibodies can reach, with medium confidence; UniProt predicts a signal peptide or a membrane-spanning region.
Gene: Protein-coding gene on chromosome X (154,219,756 to 154,233,286, forward strand). Ensembl gene ENSG00000166160.
Subcellular location: Cell membrane; Photoreceptor outer segment membrane
Gene Ontology:
Molecular function: G protein-coupled photoreceptor activity; G protein-coupled receptor activity
Biological process: visual perception; absorption of visible light; cellular response to light stimulus; G protein-coupled receptor signaling pathway; phototransduction; transducin-mediated opsin signaling pathway
Cellular component: cone photoreceptor disc membrane; photoreceptor outer segment; plasma membrane; membrane
Homologues: Orthologues: chimpanzee OPN1LW (99% identical), macaque OPN1MW3 (98% identical), macaque OPN1LW (96% identical), dog OPN1LW (90% identical), rabbit OPN1MW (88% identical), rat Opn1mw (88% identical), guinea pig Opn1mw (81% identical), tropical clawed frog opn1lw (79% identical), mouse Opn1mw (79% identical), zebrafish opn1lw1 (76% identical), zebrafish opn1lw2 (76% identical). Paralogues in human: OPN1MW (100% identical), OPN1MW3 (100% identical), OPN1LW (96% identical), RHO (43% identical), OPN1SW (42% identical), OPN3 (26% identical), OPN4 (24% identical), RRH (23% identical), OPN5 (20% identical).
Diseases named in the same sentence as OPN1MW2 in open-access papers:
OPN1MW2 is named in the same sentence as 1 disease in open-access papers, as found by Europe PMC text mining. Sharing a sentence is not in itself a finding about the gene and the disease.
OPN1MW2 shares sentences with these, for which no sentence is quoted: retinal degeneration (1 paper).